TFAP2B (transcription factor AP-2 beta)
Diseases named in the same sentence as TFAP2B in open-access papers (continued):
Sharing a sentence is not in itself a finding about the gene and the disease.
Char syndrome (continued). "Loss of Tfap2b results in altered Bmp expression that may cause the heart-limb defects observed in Tfap2b mouse mutants and Char syndrome patients." (PMID 21829553, 2011). "Alternatively, given that the mouse model represents a Tfap2b loss of function, whereas Char syndrome is inherited in a dominant manner suggestive of TFAP2B haploinsufficiency, these specific genetic alterations might result in a different spectrum of eye pathology." (PMID 27483349, 2016). "As homozygous deletion of Tfap2b or Tfap2b is lethal in mice, we used heterozygous deletion, thus mimicking the conditions that lead to CHAR syndrome in humans." (PMID 37198238, 2023). "qRT-PCR analysis of TFAP2B showed a slight increase in mRNA levels for the variants associated with craniosynostosis and CIPO, while missense variants associated to Char syndrome showed a slight decrease of transcript levels when compared to the wild type." (PMID 35874825, 2022). "The mutation in the aptf-2(qm27) allele lies in the basic region of the DNA binding domain, a region that was defined as a mutation hotspot for BOFS and Char Syndorme in the human TFAP2A and TFAP2B genes." (PMID 27176626, 2016). "Consistently, hand anomalies affect only posterior digits in Char syndrome patients and Tfap2b−/− mice." (PMID 21829553, 2011). "Given the spectrum of human midfacial anomalies associated with disrupted functions of TFAP2A (branchio-oculo-facial syndrome), TFAP2B (Char syndrome), and ALX1, ALX3 and ALX4 (frontonasal dysplasia), these findings link features of previously disparate disorders into a shared genetic hierarchy." (PMID 38063857, 2024). "Since we have now linked TFAP2B variants to PIPO, it will be interesting to evaluate if GI complaints are also present when assessing other obvious malformations, such as the ones described for Char syndrome and craniosynostosis." (PMID 35874825, 2022). "The persistent ductus arteriosus has been associated with chromosomal abnormalities in 10% of the cases and TGFBeta signaling abnormalities, as in Marfan or Loeys Dietz, to TFAP2B in Char syndrome and to TFAP2B, TNF-RAF1, prostacyclin synthase in premature and term infants." (PMID 34436233, 2021). "Aside from an interesting overlap in TFAP2B which is known to cause Char syndrome, the majority of our newly identified genetic loci have not been previously implicated in human facial development, facial dysmorphic syndromes, or animal mutant models." (PMID 27560698, 2016). "In this report, we described that transcription factor Tfap2b played a critical role in the development and remodeling of mouse ductus arteriosus as well as in the limb patterning, elucidating the pathogenesis of Char syndrome on a molecular basis." (PMID 21829553, 2011). "Furthermore, biochemical studies suggest that dominant mutations in TFAP2A or TFAP2B – resulting in branchio-oculo-facial syndrome (MIM: 113620) or Char syndrome (MIM: 169100), respectively – create mutant proteins that may interfere with other TFAP2 paralogs." (PMID 38063857, 2024). "As yet, there is no substantial evidence linking TFAP2B to human eye disease; however, this gene is mutated in Char syndrome, a rare dominantly inherited condition that is associated with patent ductus arteriosus, facial dysmorphology and digit defects as well as sleep disorders." (PMID 27483349, 2016). "TFAP2B is the most studied gene in the development of PDA, since it was described as being part of Char syndrome, the phenotype of which may include PCA." (PMID 37568921, 2023). "Therefore, although it is too early to present TFAP2B as a new CIPO gene since only one patient has been identified, our results suggest that a better characterization of Char syndrome and syndromic craniosynostosis patients is needed, to improve counselling and define optimal treatment strategies." (PMID 35874825, 2022).
Char syndrome (continued). "Genetic defects in TFAP2B/Tfap2b genes result in ARPKD-like phenotype in mice while humans with Char syndrome have no renal phenotype." (PMID 36710876, 2022).
breast carcinoma (10 papers, 2010 to 2023). "We further show that DRAGON can identify multi-omic biomarkers, as exemplified by the combination of promoter methylation and gene-expression of TFAP2B (Transcription Factor AP-2 Beta), which is strongly associated with the basal-like breast cancer subtype." (PMID 36533448, 2023). "In particular, we identify Transcription Factor AP-2 Beta (TFAP2B) as a potential multi-omic biomarker for basal-type breast cancer." (PMID 36533448, 2023). "TFAP2B is also expressed in breast tissue, where it is thought to coordinate HER2 and ER and has been associated with breast cancer prognosis." (PMID 33113958, 2020). "Of the 43 differentially methylated genes associated with breast cancer risk in the individual CpG sites analysis of normal breast tissue main analysis, LHX2 was included in three DMRs, TFAP2B in two DMRs, JAKMIP1 in one DMR, and SEPT9 in one DMR." (PMID 33113958, 2020). "It has also been shown that the TFAP2B gene product is tumor promoting in breast cancer and appears to be highly expressed in breast cancer cell lines and in tumor tissues of breast cancer patients." (PMID 30975199, 2019). "Conversely, TFAP2A and TFAP2B correlated with good overall and disease-free survival in breast cancer patients." (PMID 29439714, 2018). "Although the ERBB2 gene is frequently amplified in HER2+ breast cancer, upregulation of the TFAP2B gene provides an additional mechanism for over-expression of the ErbB2/HER2 protein." (PMID 22343619, 2012). "Several of these genes have been linked to breast cancer (MAPT, HMGCS2, NR2F2, TFAP2B, NTN4, SEC14L2 and LTF)." (PMID 21209903, 2010). "In HCC, slow-growing luminal breast cancer, and cervical cancer, TFAP2B inhibits EMT and Wnt/β-catenin signaling to limit tumor growth and migration, which may be related to the Slug and Snail signaling pathways and loss of E-cadherin and low Ki67." (PMID 37291585, 2023). "Using mRNA sequencing and proteomic data from TCGA and CPTAC of 24 different solid tumors, we identified six potential genes that are specifically upregulated in breast carcinoma: NAT1, MGP, SCGB2A2, LMX1B, TFAP2B, and TRPS1." (PMID 36284362, 2022).
lung carcinoma (8 papers, 2014 to 2025). "Our results therefore suggest that the antitumor effect of TFAP2B knockdown in lung cancer cells is associated with the increased activation of the cytochrome-c and caspase-dependent apoptotic pathway." (PMID 24766673, 2014). "To further confirm the significant association of TFAP2B expression with lung cancer cell survival and clinical outcome, we verified the essential role of TFAP2B in regulating lung cancer growth in vivo." (PMID 24766673, 2014). "In the present study, we examined the expression of TFAP2B at protein levels in lung cancer cell lines and tumor tissues, evaluated the effect of TFAP2B knockdown or overexpression on lung cancer cell growth, and further elucidated the underlying molecular mechanisms." (PMID 24766673, 2014). "The gene TFAP2B, for which the genetic variation was implicated with adipocytokine regulation and type 2 diabetes mellitus, had been suggested to play a potential oncogenic role by regulating cancer cell growth and was previously identified as a promising therapeutic target for lung cancer." (PMID 29297280, 2017). "TFAP2B knockdown by siRNA significantly attenuated cell growth and induced apoptosis in NSCLC cells in vitro and in a lung cancer subcutaneous xenograft model; conversely, upregulation of TFAP2B yielded an opposite effect." (PMID 29439714, 2018). "In this study, we evaluated the biological role and clinical significance of TFAP2B in lung cancer carcinogenesis." (PMID 24766673, 2014). "The role of TFAP2B in lung cancer growth was further confirmed in vivo using a lung cancer xenograft model." (PMID 24766673, 2014). "Among the cell lines examined, the lung cancer cell lines expressed high levels of TFAP2B protein, though the expression of TFAP2B was faint in normal human lung cell lines." (PMID 24766673, 2014). "We also demonstrated the TFAP2B-mediated regulation of tumor growth in a A549 lung cancer xenograft mouse model in vivo." (PMID 24766673, 2014). "An immunohistochemistry analysis revealed that TFAP2B was abundantly accumulated in the cytoplasm of lung cancer cells." (PMID 24766673, 2014). "TFAP2B knockdown by siRNA significantly inhibited cell growth and induced apoptosis in NSCLC cells in vitro and in a lung cancer subcutaneous xenograft model, whereas TFAP2B overexpression promoted cell growth." (PMID 24766673, 2014). "In this study, we showed that the induction of apoptosis in human lung cancer cells by TFAP2B knockdown was mediated by cytochrome-c and caspase-dependent apoptosis pathways." (PMID 24766673, 2014). "We demonstrated the high expression of TFAP2B in lung cancer cells, tumor tissues, and lung adenocarcinoma samples compared to normal cells and normal human organ tissues." (PMID 24766673, 2014). "The analysis of TFAP2B gene in LUSC subtype revealed that significantly lower expression level was observed at stage 4 of lung cancer vs. stage 1 (p = 0.0423), which may indicate inhibition of TFAP2B gene expression during tumor development." (PMID 36831334, 2023). "The tumor-infiltration immune cells, in which the expression of the TFAP2B gene correlates positively, are B lymphocytes in both subtypes of lung cancer (LUAD p = 0.0353, LUSC p < 0.001) and, additionally, negatively with dendritic cells in the case of squamous cell carcinoma (p = 0.0406)." (PMID 36831334, 2023). "We first examined the expression of TFAP2B in lung cancer cell lines and tumor tissues." (PMID 24766673, 2014). "Then we investigated the molecular mechanisms by which TFAP2B knockdown or overexpression regulated lung cancer cell growth, angiogenesis and apoptosis, and further confirmed the role of TFAP2B in tumor growth in a lung cancer xenograft mouse model." (PMID 24766673, 2014). "These in vivo results were consistent with those observed in vitro and indicated that TFAP2B could be a useful therapeutic target for lung cancer." (PMID 24766673, 2014).
lung carcinoma (continued). "Our results demonstrated that TFAP2B might regulate lung cancer cell proliferation by targeting ERK/p38, VEGF/PEDF, and caspase-dependent signaling pathways." (PMID 24766673, 2014). "Our findings provide new insight into the understanding of the biological role of TFAP2B in lung cancer and suggest that TFAP2B could serve as a novel therapeutic target for lung cancer treatment." (PMID 24766673, 2014). "Moreover, we demonstrated that the knockdown of TFAP2B using DC-based TFAP2B shRNA nanoparticles markedly inhibited tumor growth in a lung cancer xenograft mouse model, confirming the role of TFAP2B in tumor growth and survival." (PMID 24766673, 2014). "Therefore, these in vivo experiments confirmed the tumor-inhibition effects by TFAP2B knockdown in vitro and provide a rationale for the pharmacologic investigation of TFAP2B as a novel therapeutic target in lung cancer cells." (PMID 24766673, 2014). "TFAP2B high expression stimulated cancer progression through activation of many signaling pathways as; caspase and ERK/p38 in lung cancer." (PMID 32856873, 2020). "We first detected the expression of TFAP2B at protein levels in human normal cell lines (fibroblasts, HBE, 293) and lung cancer cell lines (H460, H1299, A549) by Western blotting." (PMID 24766673, 2014). "Our findings suggest that TFAP2B overexpression might help to identify NSCLC patients with a poor prognosis and could therefore serve as a potential prognostic biomarker and therapeutic target for lung cancer." (PMID 24766673, 2014). "However, the biological roles and clinical significance of TFAP2B and its precise molecular mechanisms in lung cancer have not been reported." (PMID 24766673, 2014). "Positive staining of TFAP2B was observed in lung adenocarcinoma tissue but not in adjacent normal lung cells, suggesting that TFAP2B might be a potential biomarker of lung cancer." (PMID 24766673, 2014). "To confirm the involvement of the ERK/p38 MAPK signaling pathway in the TFAP2B-mediated regulation of cell growth, we analyzed the effects of the ERK and p38-selective inhibitors (U0126 and SB03580) on TFAP2B siRNA-mediated inhibition of cell viability in lung cancer cells." (PMID 24766673, 2014).
neuroblastoma (8 papers, 2006 to 2023). Neuroblastoma (NB) is the most common solid, extracranial childhood tumor. "This was associated with elevated expression of neuroblastoma (e.g. Phox2b), sympatho-adrenal (e.g. Th), neural (e.g. Gap43), neural stem cell (e.g. Msi1) and neural crest cell markers (e.g. Tfap2b)." (PMID 37246217, 2023). "From single-cell transcriptomic analyses, in neuroblasts and low-risk neuroblastoma, TFAP2B shows high transcription factor activity." (PMID 37291585, 2023). "Dysregulation of TFAP2B in neuroblastoma cells has previously been associated with aberrant promoter-methylation, so we investigated DNA methylation as a potential mechanism." (PMID 35246212, 2022). "By contrast, the high TFAP2B expression is strongly associated with favourable prognosis in neuroblastoma and is linked to noradrenergic neuronal differentiation or senescence." (PMID 31493794, 2019). "Moreover, TFAP2B can interact with EP300 (histone acetyltransferase) to execute its critical transcriptional regulatory function in high-risk pediatric neuroblastoma." (PMID 37291585, 2023). "Loss of TFAP2B is observed in high-risk neuroblastomas and progressive tumors." (PMID 37291585, 2023). "In primary neuroblastomas, low TFAP2B expression is also significantly related to CpG methylation of the TFAP2B locus." (PMID 37291585, 2023). "TFAP2B is important for noradrenergic neuronal differentiation of neuroblastoma cells in vitro and is dysregulated by aberrant promoter methylation." (PMID 35246212, 2022). "Collectively these observations are consistent with earlier findings and strongly suggest that TFAP2B is a tumor-suppressor in neuroblastoma with decreased expression in the presence of promoter methylation." (PMID 35246212, 2022). "We first investigated TFAP2B, which is a retinoic acid-induced transcriptional activator that mediates noradrenergic neuronal differentiation of neuroblastoma cells in vitro." (PMID 35246212, 2022). "Our independent validation of this finding is additional evidence that TFAP2B is an important tumor suppressor in neuroblastoma." (PMID 35246212, 2022). "In the SEQC/MAQC-III Consortium data, TFAP2B expression is decreased in stage 4 or metastatic neuroblastomas and low expression of TFAP2B is associated with worse event-free survival outcomes in non-MYCN amplified neuroblastoma patients." (PMID 35246212, 2022). "Moreover, low TFAP2B expression was reported in primary neuroblastomas, which correlated with poor prognosis via promoting proliferation and cell cycle progression." (PMID 29439714, 2018).
Patent ductus arteriosus (8 papers, 2014 to 2022). In utero, the ductus arteriosus (DA) serves to divert ventricular output away from the lungs and toward the placenta by connecting the main pulmonary artery to the descending aorta. "DNA polymorphisms in PTGIS and TFAP2B have been identified as risk factors for patent ductus arteriosus (PDA) in a population composed of preterm infants with European genetic ancestry but not in more genetically diverse populations." (PMID 33837257, 2022).
melanoma (7 papers, 2017 to 2025). A malignant, usually aggressive tumor composed of atypical, neoplastic melanocytes. "We next asked whether ALDH-associated melanoma stem cell phenotypes are directly regulated by TFAP2B." (PMID 38963759, 2024). "Along the other branch, we observed upregulation of the NFI transcription factors, and less well-studied transcription factors in melanoma biology such as TFAP2B and TFAP2C (AP2 transcription factors)." (PMID 38183207, 2025). "When comparing AUCell expression scores of the Tfap2b regulon with our ALDHHigh enriched gene set across 16,700 single melanoma cells, originating from five primary mouse murine lesions, we detected significant co-expression of both transcriptional programs." (PMID 38963759, 2024). "In contrast, TFAP2A, a related family member expressed in proliferative melanoma that shares near-identical binding motif with TFAP2B, was negatively correlated with ALDH1A3." (PMID 38963759, 2024). "In agreement with our findings in human melanoma, we found that aldh1a3 was the most enriched ALDH family isoform in the ALDHHigh cells, together with high tfap2b, sox2, and sox10, while melanoma cells with ALDHLow activity expressed irf1b." (PMID 38963759, 2024). "The more interesting ones, confirmed by the bibliography on melanoma, are as follows: USP15, TIPIN, TMC5, TYMP, USP19, USP8, and TFAP2B." (PMID 38928466, 2024). "Indeed, AP-2 family members such as TFAP2A, TFAP2B, and TFAP2C have been shown to be involved in different cancer types such as glioblastoma, melanoma, acute myeloid leukemia, pancreatic cancer, and colorectal cancer." (PMID 39013578, 2024). "Finally, patients with very low TFAP2B expression (H Score < first quartile H Score) did not have significantly different melanoma-specific survival but presented significantly shorter progression-free survival." (PMID 28578692, 2017). "Importantly, multivariate Cox regression analysis validated the power of OVOL1 as an indicator of melanoma-specific survival, independent of tumor thickness according Breslow and age (P < 0.05; expression of AKT3 and TFAP2B did not retain significance in multivariate analysis)." (PMID 28578692, 2017).
diabetes (5 papers, 2011 to 2020). "Both of the approaches (MR + COLOC and MR + eCAVIAR) have highlighted shared causal SNPs of BMI and diabetes for four genes (TFAP2B, TCF7L2, FTO and ZC3H4)." (PMID 32366963, 2020). "In our analysis, both MR + COLOC and MR + eCAVIAR have consistently shown evidence for causal effects on diabetes mediated by BMI for four genes (TFAP2B, TCF7L2, FTO and ZC3H4)." (PMID 32366963, 2020). "Although genetic variations of TFAP2B are associated with adipocytokine regulation and type 2 diabetes mellitus, the role of TFAP2B in regulating cancer-related gene expression remains largely unknown." (PMID 24766673, 2014). "Notably, the relationships of ETS translocation variant 4 (Etv4) and transcription factor AP-2 beta (Tcfap2b) to adipogenesis, which is strongly related to diabetes, have been reported, together with their association with the other pathways." (PMID 23046543, 2012). "Thus, the TFAP2B gene may play an important role of the underlying mechanisms of diabetes, where BMI is a mediator." (PMID 32366963, 2020).